MTOR (mechanistic target of rapamycin kinase)
Diseases named in the same sentence as MTOR in open-access papers (continued):
Sharing a sentence is not in itself a finding about the gene and the disease.
kidney cancer (continued). "Most of these mutations assemble in six different regions of the c-terminal region of mTOR in several cancer types, and one is specifically abundant in kidney cancer, all of which maintain the sensitivity to mTOR inhibition by pharmacological therapies." (PMID 30754640, 2019). "Our data also suggest that brain and kidney cancer have patterns of transcriptomic dysregulation in the PI3K/AKT/MTOR axis that are similar to those found in ASD." (PMID 31007884, 2019). "In this study, we investigated the impact of molecular‐targeting agents including PDGF‐R and mTOR inhibitors on the tumor stroma of human kidney cancer and examined the efficacy of combination therapy with these agents against this disease." (PMID 28834289, 2017). "The FDA also approved the use of mTOR inhibitor CCI-779 in 2007 for treatment of advanced kidney cancer." (PMID 29083380, 2016). "Targeting mTOR is one of the therapeutic strategies for many mTOR-related tumorigenesis including kidney cancer." (PMID 26418749, 2015). "Hyperactivation of Akt resulted in significant decrease in tuberin and hyperactivation of mTOR suggesting that tuberin is a major tumor suppressor protein involved in the development of kidney cancer." (PMID 24797175, 2014). "Previous research found that ESCO2 affects the AKT/mTOR pathway in kidney cancer." (PMID 40657363, 2025). "MTOR mutations are relatively uncommon in kidney cancer, with an incidence of 3% in chRCC and no previously reported incidence in RO tumours." (PMID 39271965, 2024). "This study found and confirmed for the first time that MIAC directly binds to AQP2 inhibiting the expression of EREG, EGFR and the activation of downstream PI3K/AKT and mTOR signaling pathways to achieve the inhibitory effect of kidney cancer growth and metastasis." (PMID 36117171, 2022). "Comprehensive characterization of the regulation of gene expression by the HIF–VHL and mTOR pathways is crucial to understanding the biology of VHL-defective kidney cancer, particularly as agents targeting both these pathways are being deployed therapeutically." (PMID 36097292, 2022). "Since targeting the mTOR pathway is a part of the chemotherapy regimen for advanced kidney cancer patients, we next assessed whether the responsiveness to this agent was correlated with the extent of genomic aberrations at 3p and at 14q." (PMID 32492043, 2020). "In kidney cancer cells, the ability of mTOR to promote Hif1α translation has also been studied." (PMID 27148974, 2016). "Outside of the transplant population, mTOR inhibitors are used to treat kidney cancer." (PMID 26108799, 2015). "Given the role of the mTOR pathway in facilitating the kidney cancer growth, the reduced incidence observed in our study may reflect an effect of sirolimus in preventing small tumors from growing to a clinically detectable stage." (PMID 26108799, 2015). "In summary, our findings shed new insight into the biology of mTOR as it pertains to kidney cancer." (PMID 26255626, 2015). "mTOR was reported to be aberrantly activated during tumorigenesis, and it was found to have played a crucial role in the initiation and progression of various malignant tumors, including breast, prostate, lung, liver, and kidney cancers (Posadas, Limvorasak & Figlin, 2017)." (PMID 34458019, 2021). "ESCO2 is significantly upregulated in kidney cancer tissues, and ESCO2 knockdown inhibits cancer cell growth, invasion, and migration by regulating the AKT/mTOR pathway." (PMID 40657363, 2025). "We found mTOR and dual PI3K/mTOR inhibitors, such as sapanisertib, everolimus and omipalisib, to show significant and increased specific activity against kidney cancer cell lines, which is consistent with other reports." (PMID 39186767, 2024). "This emphasizes the significance of employing payloads, which can effectively target mTOR signaling pathways, in designing ADC targeting strategies against kidney cancer." (PMID 39186767, 2024).
kidney cancer (continued). "Studies have shown two cellular-molecular pathways for the growth of kidney cancer cells: the pathway involved with VEGF and the second pathway, the mammalian target of rapamycin (mTOR)." (PMID 36703202, 2023). "Analyses of the interplay of HIF and mTOR reveal that specific classes of HIF1A and HIF2A transcriptional target gene manifest different sensitivity to mTOR, in a manner that supports combined use of HIF2A and mTOR inhibitors in treatment of kidney cancer." (PMID 36097292, 2022). "We next applied HP5 to the analysis of mTOR pathways, which are frequently dysregulated along with hypoxia signaling pathways in VHL-defective kidney cancer." (PMID 36097292, 2022). "Widely recognised kidney cancer targeted agents fall into two categories, TKI and mTOR inhibitors, acting through VHL/HIF/VEGF and PI3K/AKT/mTOR signalling pathways respectively." (PMID 36741716, 2022). "Overall, these findings indicate that full upregulation of the glycolysis pathway requires both HIF and mTOR activity, as would be predicted to occur in VHL-defective kidney cancer with mTOR hyperactivation." (PMID 36097292, 2022). "Using a new technology to measure the ribosome load of mRNAs resolved by their TSS, we have characterized the pan-genomic interplay of HIF- and mTOR-dependent transcriptional and translational regulation in VHL-defective kidney cancer cells." (PMID 36097292, 2022). "Despite the advent of FDA-approved therapeutics to a limited number of available targets (kinases and mTOR), PFS of kidney cancer (RCC) has been extended only one to two years due to the development of drug resistance." (PMID 25461627, 2014). "In the present study we demonstrated dose-dependent antitumor effect of PI3K/mTOR dual inhibitor NVP-BEZ235 in bladder, prostate and kidney cancer cell lines." (PMID 24969552, 2014). "Although LPA is elevated (along with autotaxin (ATX)) in kidney cancers and can promote malignancy of patient-derived tumor cells, the role of this mitogenic lipid in chemotherapeutic resistance with the mTOR inhibitor, TEMS, has not yet been explored." (PMID 32492043, 2020). "Finally, in kidney cancer, MARCKS inhibition with MPS peptide synergistically interacted with regorafenib treatment and decreased survival of kidney cancer cells through inactivation of AKT and mTOR (mechanistic target of rapamycin)." (PMID 29295532, 2017). "It has been reported that kidney cancer tissues display a low expression of METTL3 that not only promotes the proliferation, growth, and colony formation of the cancer cells via the PI3K/Akt/mTOR pathway but also activates the EMT to facilitate the migration and invasion of the cells." (PMID 33061938, 2020).
cholangiocarcinoma (62 papers, 2009 to 2026). A carcinoma that arises from the intrahepatic biliary tree (intrahepatic cholangiocarcinoma) or from the junction, or adjacent to the junction, of the right and left hepatic ducts (hilar cholangiocarcinoma). "A notable case report highlighted a dramatic response to mTOR-targeted therapy in a patient with intrahepatic cholangiocarcinoma harboring TSC1 and ARID1A mutations, indicating potential oncogenic dependence on mTOR in certain subtypes." (PMID 41300430, 2025). "Kulkarni et al122 reported that ANO1 can interact with the mTOR pathway to regulate the cytoskeleton, survival, proliferation, and migration in cholangiocellular carcinoma, but the specific underlying mechanisms need to be further investigated." (PMID 38685684, 2024). "The PI3K/AKT/mTOR signaling pathway is frequently activated in cholangiocarcinoma, driving tumor development, progression, and resistance to chemotherapy." (PMID 41300430, 2025). "Collectively, these findings highlight tiliacorinine’s strong binding affinities to pivotal cholangiocarcinoma-related targets, including MTOR, SRC, MMP9, and MAPK1, underscoring its potential as a promising multi-target therapeutic candidate." (PMID 41300430, 2025). "So far, two independent studies of small cohorts of cholangiocarcinoma patients receiving FGFR targeted therapy reported the acquisition of MAPK or PI3K/MTOR pathway alterations." (PMID 40260297, 2025). "PIK3CA encodes the p110α subunit of PI3K, a key player in the PI3K/AKT/mTOR pathway, which is often dysregulated in cholangiocarcinoma." (PMID 41300430, 2025). "Apitolisib treatment strongly reduced the phosphorylation of AKT and mTOR and decreased growth in two cholangiocarcinoma (CCA) cell lines, SNU1196 and SNU478." (PMID 37046703, 2023). "This encompasses historically efficacious therapeutics in unselected advanced cholangiocarcinoma such as the mTOR inhibitor Everolimus27, now included in new Phase II solid cancer trials (NCT04591431)." (PMID 37095160, 2023). "Reportedly, lncRNA HAGLROS regulates lipometabolism reprogramming in intrahepatic cholangiocarcinoma via mTOR axis." (PMID 35846429, 2022). "In the present study, the results revealed that Tan-IIA significantly inhibited the level of PI3K, p-Akt, mTOR and p-mTOR protein in Cholangiocarcinoma cells." (PMID 34588580, 2021). "Further mechanism studies demonstrated that Tan-IIA promoted apoptosis and suppressed malignant growth, invasion, and migration of Cholangiocarcinoma cells through inhibited PI3K/Akt/mTOR signaling pathway." (PMID 34588580, 2021). "Our findings indicated that Tan-IIA induced Cholangiocarcinoma cells apoptosis via inhibition of the Akt/mTOR pathway." (PMID 34588580, 2021). "When targeting glucose metabolism, rapamycin, which inhibits glycolysis through suppressing the mTOR pathway, also shows synergistic antitumor activity with salubrinal in cholangiocarcinoma cells." (PMID 34572286, 2021). "FGFR2-SHTN1 has been previously identified in cholangiocarcinoma and has been linked to increased phosphorylation of PI3K/AKT and the mechanistic target of rapamycin kinase (mTOR) pathways in in vitro assays in NIH-3T3 and 293T-engineered cells." (PMID 34068816, 2021). "The present study suggested that Tan-IIA inhibited the proliferation, invasion, and migration of Cholangiocarcinoma cells by inhibiting the PI3K/Akt/mTOR pathway." (PMID 34588580, 2021). "In the present study, we confirmed that mTOR signaling is the most significantly affected pathway in the human intrahepatic biliary epithelial cell line (HIBEpiC) and human cholangiocarcinoma cell line (RBE) by KEGG pathway enrichment analysis." (PMID 34716294, 2021). "A search for phase II and III trials was operated on clinicaltrial.gov (data of entry 2020-01-15) combining terms such as cholangiocarcinoma, autophagy, mTOR, AKT, PI3K, chloroquine and hydroxychloroquine and obtaining a limited set of studies." (PMID 32143356, 2020).
cholangiocarcinoma (continued). "Ectopic overexpression of miR-199a-3p in cholangiocarcinoma cells increased sensitivity to cisplatin by targeting the mTOR signaling pathway." (PMID 33007962, 2020). "The presence of the tyrosine kinase-AKT-mTOR axis in the carcinogenesis of cholangiocarcinoma has provided us with an opportunity to evaluate the therapeutic role of an mTOR inhibitor, rad001, in the management of this disease." (PMID 29666220, 2018). "This study aims to investigate a novel therapeutic regimen [gemcitabine plus everolimus (rad001), an mTOR inhibitor] for cholangiocarcinoma." (PMID 29666220, 2018). "The mTOR pathway is dysregulated in various cancers including cholangiocarcinoma, making mTOR an important target for the development of new anticancer drugs." (PMID 29666220, 2018). "In conclusion, our study demonstrates that miR-199a-3p can increase the cisplatin sensitivity of cholangiocarcinoma cell lines by inhibiting the mTOR signaling pathway and MDR1 expression." (PMID 28422725, 2017). "Results from our study imply that miR-199a-3p plays a critical role as an inhibitor of mTOR in cholangiocarcinoma." (PMID 28422725, 2017). "Our results, for the first time, prove that miR-199a-3p can enhance cisplatin sensitivity in cholangiocarcinoma cell lines by regulating the mTOR signal pathway and MDR1." (PMID 28422725, 2017). "Previous studies, have demonstrated the efficacy of MK2206 as a single agent in other cancer types or in synergistic combination with RAD001 (an mTOR inhibitor) in cholangiocarcinoma cells in vitro." (PMID 25674039, 2015). "Local delivery of paclitaxel from a PEM inhibited growth of pancreatic/cholangiocarcinoma tumors in nude mice by suppressing angiogenesis via the mTOR and inducing apoptosis signal pathway." (PMID 25983747, 2015). "Recently, it has been reported that treatment of cholangiocarcinoma cells with oxaliplatin increased the phosphorylation of mTOR." (PMID 25347345, 2014). "The effect of PI3K and mTOR inhibition on oxaliplatin sensitivity of cholangiocarcinoma cells is examined." (PMID 19128511, 2009). "The collective evidence indicates that Medicarpin’s anticipated mTOR inhibition may yield significant therapeutic benefits in cholangiocarcinoma by modulating this highly active carcinogenic pathway." (PMID 41465766, 2025). "that induced apoptotic cell death of cholangiocarcinoma via AKT/mTOR signaling pathway." (PMID 39446747, 2024). "promoted cancer cell death, including cholangiocarcinoma cells via inhibition of AKT/mTOR pathway." (PMID 39446747, 2024). "In addition, Kulkarni et al122 reported that ANO1 can interact with mTOR to regulate the cytoskeleton, survival, proliferation and migration in cholangiocarcinoma." (PMID 38685684, 2024). "A second tier of high frequency mutations were identified in oncogenes not typically associated with cholangiocarcinoma, including mTOR (17%, 7/42 cases) and ABL1 (14%, 6/42 cases)." (PMID 37095160, 2023). "In a study evaluating patient-derived models of FGFR2-fusion-positive cholangiocarcinoma, inhibition of EGFR potentiated responses to FGFR inhibitors, durably suppressing MEK/ERK and mTOR signaling, increasing apoptosis, and causing marked tumor regressions in vivo." (PMID 35444941, 2022). "Furthermore, phosphorylated Fyn activates mTOR in HEK293T cells and skeletal muscle, and knockdown of Fyn inhibits phosphorylation of mTOR in cholangiocarcinoma cell lines." (PMID 34863087, 2021). "For instance, the high expression of TRIM59 in cholangiocarcinoma cells could regulate cell proliferation via the phosphatidylinositol-3-kinase (PI3K)/AKT/mammalian target of rapamycin (mTOR) signaling pathway." (PMID 33791238, 2021). "Furthermore, pretreatment of Cholangiocarcinoma cells with the 740 y-p (PI3K agonist) abolished the effects of Tan-IIA on the restrain PI3K, p-Akt, mTOR, and p-mTOR in Cholangiocarcinoma cells." (PMID 34588580, 2021).
cholangiocarcinoma (continued). "Firstly, mTOR inhibitors could be used alone or in combination with other agents in the patients with advanced cholangiocarcinoma refractory to standard treatments." (PMID 30682771, 2019). "There are two settings for mTOR inhibitors used in the patients with advanced cholangiocarcinoma." (PMID 30682771, 2019). "Further, we demonstrate that miR-199a-3p could increase the cisplatin sensitivity of cholangiocarcinoma cell lines by inhibiting the activity of the mTOR signaling pathway, decreasing the synthesis of MDR1, and increasing the degradation of MDR1." (PMID 28422725, 2017). "Rescue experiments proved that miR-199a-3p could increase the cisplatin sensitivity of cholangiocarcinoma cell lines by regulating mTOR expression." (PMID 28422725, 2017). "To further prove that miR-199a-3p could affect the sensitivity of cholangiocarcinoma to cisplatin by regulating the activity of the mTOR signaling pathway, we performed a rescue experiment." (PMID 28422725, 2017). "In conclusion, miR-199a-3p could increase cisplatin sensitivity of cholangiocarcinoma cell lines by inhibiting the activity of the mTOR signaling pathway and decreasing the expression of MDR1." (PMID 28422725, 2017). "As we described in our previous study, whether activation of the mTOR pathway promotes the development of cholangiocarcinoma or predicts a poor prognosis remains controversial." (PMID 28241849, 2017). "Above all, we demonstrated that miR-199a-3p could enhance the cisplatin sensitivity of cholangiocarcinoma by inhibiting the mTOR pathway." (PMID 28422725, 2017). "In addition, we demonstrated that oxaliplatin-treated cholangiocarcinoma cells exhibit high levels of Akt and mTOR phosphorylation as a result of PI3K activation." (PMID 19128511, 2009). "In this study, we hypothesize that inhibition of PI3K or its downstream target, mTOR, may be increase oxaliplatin efficacy in treating cholangiocarcinoma." (PMID 19128511, 2009). "Therefore, based on the results of RNA-Seq analysis, we further explored whether DCLK1 promotes the development of cholangiocarcinoma by activating the PI3K/AKT/mTOR signaling pathway." (PMID 38980538, 2024). "Of note, mTOR is considered a potential therapeutic target in cholangiocarcinoma (CCA), since elevated mTOR activity is positively correlated with activated EMT." (PMID 35454770, 2022). "Secondly, mTOR inhibitors could be used in combination with standard treatment in patients with treatment-naïve advanced cholangiocarcinoma to investigate the possibly better response, progression-free survival and overall survival than conventional standard treatment." (PMID 30682771, 2019). "However, no study has reported the relationship between miR-199a-3p and mTOR in cholangiocarcinoma." (PMID 28422725, 2017). "However, little is known about the role of mTOR in cholangiocarcinoma." (PMID 28422725, 2017). "The PI3K/Akt/mTOR pathway plays an important role in CCA pathogenesis as evidenced by its reported over activation in both intra and extrahepatic cholangiocarcinoma." (PMID 25674039, 2015). "How do the PI3K/AKT/mTOR and AMPK/Nrf2 pathways work together to regulate amino acid metabolism in cholangiocarcinoma (CCA)?" (PMID 41513616, 2026). "We chose Infigratinib, a selective FGFR1-3 inhibitor to target FGFR signaling (FDA-approved for treatment of cholangiocarcinoma with an FGFR2 fusion), and Everolimus which inhibits the formation of the mTOR complex, for testing in combination with BCL2i." (PMID 40568132, 2025). "Through activation of the AKT/mTOR pathway, FGFR2 reduces the sensitivity of cholangiocarcinoma to gemcitabine." (PMID 37750089, 2023). "Mechanistically, the mTOR inhibitor rapamycin inhibits the EMT, stem-like capacity, and migration of cholangiocarcinoma in vitro and inhibits the FBXW7 silencing-induced metastasis of these cells in vivo." (PMID 35454770, 2022).